IGF1 (insulin like growth factor 1)
Diseases named in the same sentence as IGF1 in open-access papers (continued):
Sharing a sentence is not in itself a finding about the gene and the disease.
Obesity (continued). "However, participants with obesity showed no increase in serum total IGF‐1 concentration at any time point compared to pre‐exercise levels in response to exercise (p > 0.05)." (PMID 40574473, 2025). "The mechanisms that link obesity and cancer include the elevated levels of insulin, which can promote carcinogenesis, either directly through insulin receptors or indirectly by lowering IGF-binding proteins and increasing circulating IGF-1 levels, which in turn act on cancer cell receptors." (PMID 40364176, 2025). "Additionally, several studies have indicated that obesity can result in a decrease in GH secretion, leading to low-normal IGF-1 levels." (PMID 39355348, 2024). "A decrease in GH and IGF-1 levels may be considered as obesity complication in patients without a pituitary disease." (PMID 37049479, 2023). "The routine determination of GH and IGF-1 in patients with obesity is not recommended." (PMID 37049479, 2023). "Unfortunately, biochemical measurements of inflammatory cytokines, IGF-1, and leptin were not available in our study, and these may help to better clarify the relationship between obesity and bone health." (PMID 35865318, 2022). "Although in the literature the total serum levels of IGF1 does not appear to decrease in obesity, and, on the contrary, levels of bioactive IGF1 are even slightly elevated when compared to normal weighting subjects, in populations affected by steatosis and steatohepatitis this picture changes." (PMID 36557260, 2022). "The main reason for this rise in obesity, and thus diabetes and GDM problems, is due to the consumption of foods and/or diets rich in fats and sugars, which may be attributable to alterations in the insulin/IGF-1 signaling pathway." (PMID 35813659, 2022). "In addition, many hormones and cytokines altered with obesity may influence ADPKD progression, including increased levels of insulin, insulin-like growth factor 1 (IGF-1), leptin, TNF-α, and IL-6, as well as decreased adiponectin." (PMID 35350649, 2022). "Regardless of the nature of the mechanism by which IGF-1 levels are reduced by sodium selenite supplementation, it is clear that this intervention is highly effective in protecting against diet-induced obesity and conferring a multitude of additional MR-like healthspan benefits." (PMID 33783357, 2021). "The low testosterone levels in boys with obesity during puberty may hence contribute to the attenuated peak of serum IGF-1 and the lack of the growth spurt." (PMID 34386750, 2021). "However, in order to minimize this limit, we consider people with obesity without GH/IGF-1 derangement as control." (PMID 31527400, 2019). "In addition, obesity can lead to hyperinsulinemia, which can reduce the synthesis of sex hormone binding protein (SHBG) by increasing the bioavailability of insulin-like growth factor-1 (IGF-1), thereby leading to an increase in estrogen levels." (PMID 31440472, 2019). "Levels of obesity-related inflammatory indicators (i.e. free fatty acid (FFA), glutathione peroxidase (GSH-Px), human inhibin-B (IHNB), interleukin-1 (IL-1), insulin-like growth factor-1 (IGF-1), and reactive oxygen species (ROS)) also varied with degrees of BMI." (PMID 28515223, 2017). "Therefore, the present study was carried out with the aim of determining the proportion of individuals with low serum IGF-1 levels and/or failing to respond to the combined GH-releasing hormone (GHRH) plus arginine test in a cohort of FM subjects with severe obesity." (PMID 28744309, 2017). "Briefly, an inverse correlation between IGF-1 (IGF-1/IGFBP-3 ratio) circulating levels and several markers for obesity, MetS, T2D, and CVD has been found; and thus, it could indicate that low circulating levels of IGF-1 can lead to MetS and raise the risk for CVD and T2D." (PMID 26733412, 2016). "Furthermore IGF-1 level was lower in the groups of patients with different types of obesity related glomerular lesion when comparing with those without renal lesion." (PMID 27138941, 2016).
Obesity (continued). "However, there is no overall correlation between tumor latency time and mouse weight at tumor detection date, indicating that chronic treatment of X10 and IGF1 affects tumor latency directly by mitogenic signaling rather than indirectly by obesity." (PMID 25848982, 2015). "The relation between obesity and IGF-1 is complex; it is hypothesized that free IGF-1 increases with body weight until it reaches a level that triggers a negative feedback that would suppress growth hormone secretion (GH) which in turn would result in decreased IGF-1 production in the liver." (PMID 24616825, 2014). "In a murine model of obesity and chronic IGF-1 gene deficiency, diet-induced obese mice demonstrated increased local tumor growth and metastases compared to lean controls, but this was not seen in IGF-1 gene deficient mice." (PMID 21696633, 2011). "Such overexpression of TGFβ, IGF-1 and TIMP-2 has been previously reported in subcutaneous adipose tissue from obese individuals indicating that chondrocytes may also exhibit an obesity-related gene expression pattern." (PMID 20534145, 2010). "Our findings indicate that reduced muscle protein synthesis previously reported in humans with obesity following acute exercise may not be attributable to differences in the responses of circulating free IGF‐1, as its levels were comparable between participants with and without obesity in our study." (PMID 40574473, 2025). "In addition, in the absence of IGFBP-1 synthesis in obesity, IGF-1 may further induce the abnormal proliferation of endometrial cells, which is a possible pathway for endometrial cancer formation." (PMID 36755926, 2023). "Therefore, whether or not the low IGF-1 levels observed in obesity subjects are attributable to decreased GH secretion in the pituitary remains to be elucidated." (PMID 36418379, 2022). "Notably, the relationship between serum levels of IGF-1 and PAPP-A and local IGF-1 activity is unclear and may for example be dependent on body composition, inflammation, or conditions such as diabetes mellitus or obesity." (PMID 31963719, 2020). "However, while it has been reported that IGF-1 levels are high in obesity, other studies show that it is not increased or may even be decreased." (PMID 31130916, 2019). "The disconnect between the similar GH levels in DM vs non-DM patients and the difference in IGF-1 may also be explained by the effect of obesity and hyperinsulinism both increasing hepatic GH sensitivity and increasing free fatty acids, which suppress GH release." (PMID 29767287, 2018). "However, after 30 min, no changes were noted for growth hormone, insulin, and insulin-like growth factor-1, suggesting that vibration may not be an effective method for obesity treatment." (PMID 27508150, 2016). "However, the stimulatory effect of diet-induced obesity on tumor growth appeared greater in BP3KO mice, perhaps indicating that this diet-related tumor growth was driven in part by local IGF-1 bioavailability, notwithstanding the similar total circulating IGF-I levels among all groups." (PMID 27448965, 2016). "In our study, serum IGFBP‐3 concentrations increased during exercise in the control study participants without obesity alongside the total IGF‐1, which likely accounts for the absence of an increase in serum free IGF‐1 concentrations." (PMID 40574473, 2025). "We investigated the effects of acute endurance exercise on serum IGF‐1 and binding proteins of IGF‐1 in participants with and without obesity." (PMID 40574473, 2025). "In children with obesity, acute exercise does not impair increases in circulating IGF‐1 levels, supporting its use as a lifestyle intervention to modulate IGF‐1 in this population." (PMID 40574473, 2025). "Both total IGF‐1 and IGFBP‐3 serum concentrations increased significantly (p < 0.05) during exercise in the study participants without obesity but not in those with obesity, returning to basal levels immediately after exercise." (PMID 40574473, 2025).
Obesity (continued). "Serum miR-181a and miR-27a were superior in overall and obesity-related CRC diagnosis, respectively; meanwhile, IGF1 was superior in distinguishing obese from non-obese CRC patients." (PMID 38704452, 2024). "Several studies have shown negative correlations between BMI and absolute IGF-1 levels, while others reported increased circulating IGF-1 in obesity and, specifically, abdominal obesity due to elevated portal insulin levels." (PMID 37571382, 2023). "Serum levels of free IGF1 and IGFBP3, but not of total IGF1, are reported to be higher and IGFBP2 lower in children with obesity compared to control children." (PMID 32849298, 2020). "In obesity, non-esterified fatty acids and insulin inhibit IGFBP production, which increases free IGF-1 in circulation." (PMID 32586279, 2020). "We consecutively compared the IGF-1 levels and IGF-1 SDS between the morbidly obese patients without a renal lesion and those with any type obesity related glomerular lesion." (PMID 27138941, 2016). "While the attenuation of age-induced obesity in RIIβ−/− mutants does not seem to promote longevity and healthful aging by its effects on peripheral or systemic action of insulin on glucose homeostasis, it may do so by a reduction in insulin-related intracellular signaling through the IGF-1 pathway." (PMID 19536287, 2009). "IR did not correlate with the MMPs, ADAMS, ADAMTS, or IGF-1/IGFBP-1 when BMI was accounted for, suggesting that it is obesity which is accompanied by IR, rather than IR alone, that may modulate these ECM parameters in PCOS." (PMID 39796177, 2025). "In conclusion, AT may not be the major source for the obesity-related elevations in serum GHBP and IGF-1 in children." (PMID 36384443, 2022). "In both sexes, circulating levels of free IGF1, total IGF1, IGF2 and IGFBP3 are reported to be increased in humans and rodents with obesity, although some studies found no changes in total IGF1 in patients with obesity." (PMID 33202914, 2020). "However, exogenous IGF-1 expression, even though it rescues body length, BMC, and BMD, does not prevent obesity in ksr2−/− mice." (PMID 27561547, 2016). "Additionally, the IGF-1/IGFBP-3 ratio, a common rough of free IGF-1 levels, is significantly decreased in obesity, however no IGF-1 bioactivity was estimated." (PMID 26733412, 2016). "Hence, overall this strengthens the hypothesis that AT itself is not a relevant contributor to obesity-related elevations of circulating GHBP and IGF-1." (PMID 36384443, 2022).
diabetes (769 papers, 2002 to 2026). "Although some studies have attributed this cognitive decline to comorbidities such as sleep apnea, cerebral microbleeds, or diabetes, recent evidence has implicated the direct involvement of elevated GH and IGF‐1 levels." (PMID 41550023, 2026). "Patients with prostate cancer and diabetes have lower PSA and testosterone levels and higher serum FBS, HbA1c, insulin, and IGF-1 levels, along with a deranged lipid profile, leading to observed greater cancer grade and high risk in men with diabetes." (PMID 41367482, 2025). "Chronic GH and insulin-like growth factor-1 (IGF-1) overproduction cause systemic complications such as hypertension, diabetes, and cardiomyopathy." (PMID 40842744, 2025). "The association between diabetes and poor bone metabolism is likely due to decreased insulin-like growth factor-1 (IGF-1), which plays a key role in bone formation." (PMID 40722438, 2025). "The cumulative effect of the LoF was associated with diabetes, reduced insulin secretion, and higher levels of GH and IGF-1." (PMID 39137152, 2025). "Children of families with familial hypertension or diabetes have a decreased risk of being in the “low leptin/IGF-1/HbA1c” status as compared to the “normal” status." (PMID 39899498, 2025). "Data showed that serum insulin and IGF-1 were significantly elevated in prostate cancer, highest being in prostate cancer with diabetes, and they had a positive association with prostate cancer Gleason score, grade, and high risk." (PMID 41367482, 2025). "Mechanisms underlying bone loss associated with diabetes include increased formation of advanced glycation end products (AGEs), decreased insulin-like growth factor-1 (IGF-1) levels, and increased inflammatory status." (PMID 40438830, 2025). "In our study, higher IGF-1 levels were linked to lower odds of uncontrolled diabetes in elderly T2DM patients." (PMID 41393761, 2025). "Endocrine disorders are common in patients with diabetes, particularly characterized by a deficiency in insulin and insulin-like growth factor-1 (IGF-1), which leads to insufficient collagen synthesis and poor bone mineralization." (PMID 39194658, 2024). "Researchers have mentioned that the association between diabetes and cancer is due to the mitogenic effects of insulin and insulin-like growth factor 1 (IGF-1)." (PMID 39082041, 2024). "Clinical observations indicate a correlation between low systemic levels of IGF-1 and the severity of retinopathy of prematurity, and IGF-1 is implicated in diabetes." (PMID 38300646, 2024). "Our research also revealed that diabetes caused a significant elevation in the levels of IGF-1, PI3K, and AKT proteins, but after eight weeks of HIIT, the levels of these proteins decreased significantly in the training groups." (PMID 38531890, 2024). "In patients with acromegaly, a condition characterized by excessive growth hormone and IGF-1 production, there is an association between reduced life expectancy and an increased incidence of age-related diseases like diabetes." (PMID 38377027, 2024). "Obese individuals typically exhibit lower GH pulsatile secretion compared to those with normal weight, and diminished levels of GH and IGF-1 have been linked to an elevated risk of chronic conditions such as diabetes and heart disease." (PMID 39464190, 2024). "IGF-1 has been proposed as a diabetes risk biomarker, as some studies showed a lower risk of glucose intolerance or T2DM in individuals with high versus low IGF-1 concentrations." (PMID 38474344, 2024). "One potential cause of this phenomenon is the relative insulin deficiency observed in long-standing diabetes, which leads to lower levels of C-peptide and IGF-1 compared to healthy individuals." (PMID 39682196, 2024). "Whereas, the observed inverse association between diabetes and prostate cancer can be explained by the lower levels of testosterone or leptin and insulin-like growth factor 1 in men with diabetes." (PMID 37900125, 2023).
diabetes (continued). "Diabetes increases the risk of cancer through various mechanisms such as hyperinsulinemia and an increase in insulin growth factor 1 (IGF-1) secretion." (PMID 37444627, 2023). "Insulin-like growth factor (IGF) is also a possible mechanism linking diabetes and cancer, as hyperinsulinemia causes a rise in the level of free and bioactive IGF-1, which increases the underlying risk of cancer in type 2 diabetic patients." (PMID 37296304, 2023). "The other study of postmenopausal women with diabetes mellitus revealed increased serum pentosidine and decreased serum IGF-1 levels to be independently associated with loss of muscle mass." (PMID 37780552, 2023). "Our results suggest that decreased IGF-1 level is associated with restrained amino acid metabolism in NSCLC with diabetes mellitus." (PMID 36329881, 2022). "The etiology of diabetes in acromegaly is associated with increased circulating GH and IGF-1, leading to insulin resistance, increased gluconeogenesis, and hyperinsulinemia." (PMID 36105896, 2022). "The excess GH and IGF-1 of acromegaly cause a variety of harmful effects, including hypertension, diabetes, cardiac dysfunction, colonic polyps, and arthritis; all of these can be classified as conditions that become more prevalent with aging." (PMID 36063137, 2022). "Remarkably, diabetic children tend to present low BMD and decreased circulating IGF-1 levels, although associations between diabetes and bone health are typically heterogeneous and rely on diverse bone turnover biomarkers." (PMID 35334960, 2022). "The fact that these diseases share common biomarker patterns is not surprising, but interestingly, we also see the reduced risk associated with LDL and IGF-1 across all three types of diabetes." (PMID 36535980, 2022). "We examined the association between serum IGF-1 and a panel of age-associated outcomes, including vascular disease, diabetes, dementia, osteoporosis, cancer, and mortality." (PMID 36063137, 2022). "In mice, very low levels of IGF‐1 are associated with reduction in a range of diseases and conditions including cancer, diabetes, and cognitive decline and with record longevity." (PMID 35048526, 2022). "Experiments on mice have shown that a high-protein diet leads to an increased level of IGF-1 (insulin-like growth factor 1) which is correlated with a high risk of developing diabetes." (PMID 33803255, 2021). "Plant-based diets decreased diabetes risk by 27%, and dairy consumption (measured by increased IGF-1 levels) increased cancer probability by 48% (p < 0.01)." (PMID 37928317, 2021). "We also aimed to examine the associations between serum IGF-1 levels and diabetes, antipsychotic drugs, and disease duration." (PMID 33746806, 2021). "One Mendelian randomization study in the UK Biobank found associations between higher genetically determined IGF‐1 and diabetes and vascular disease, consistent with our results." (PMID 34363732, 2021). "We also examined the associations between serum IGF-1 levels and diabetes, antipsychotic drug use, and disease duration." (PMID 33746806, 2021). "For each increase in IGF-1 quartile, the risk of diabetes at hospital discharge decreased (p for trend = 0.003)." (PMID 34851758, 2021). "For example, both animals and people with CF have reduced anabolic drive secondary to lower tissue concentrations of insulin-like growth factor-1 (IGF-1) and insulin deficiency associated with CF-related diabetes." (PMID 34959966, 2021). "In acromegaly, excess growth hormone and resultant excess IGF‐1 cause a variety of detrimental effects, including hypertension, diabetes, cardiac dysfunction, and respiratory disorders." (PMID 34363732, 2021). "Seventy-eight patients (28%) had type 2 diabetes at discharge, and the highest quartile of IGF-1 levels was associated with the lowest incidence of diabetes (HR:0.40 (95%CI:0.17–0.95), p = 0.037)." (PMID 34851758, 2021).